MST1 (macrophage stimulating 1)
Diseases named in the same sentence as MST1 in open-access papers (continued):
Sharing a sentence is not in itself a finding about the gene and the disease.
male infertility (1 paper, 2024). The inability of the male to effect fertilization of an ovum after a specified period of unprotected intercourse. "Male infertility has been observed in mice with both Mst1 and Mst2 deficiency in the epididymal epithelium." (PMID 39659446, 2024). "Double deficiency of Mst1 and Mst2, upstream effectors of YAP1, has been observed in male infertility, and the Hippo pathway may affect male reproduction development, except for YAP1, MST1, and MST2." (PMID 39659446, 2024).
malignant mesothelioma (1 paper, 2021). A malignant neoplasm of the pleura or peritoneum, arising from mesothelial cells. "The association between loss of MST1 expression and poorer prognosis has been observed in other types of cancers, including malignant mesothelioma." (PMID 34885067, 2021).
meningioma (1 paper, 2025). A generally slow growing tumor attached to the dura mater. "The expression of Merlin, mammalian sterile 20-like kinases 1 and 2 (MST1/2) and Yes-associated protein (YAP) from these two meningioma cells were analyzed by Western blot." (PMID 39894505, 2025).
myocarditis (1 paper, 2024). Myocarditis is a condition that is characterized by inflammation of the heart muscle (myocardium). "We found that ICI-related myocarditis reduced Mst1 kinase activity and activated TAZ, acting as a co-activator of RORγt to promote Th17 differentiation and inhibit Treg cell development." (PMID 38236243, 2024). "Western blot data showed that XMU-MP-1 decreased the cascade of HIPPO pathway kinases as well as the expression levels of Mst1 and TEAD-1 and increased the expression of TAZ in the myocardial tissue of the ICI-related myocarditis model." (PMID 38236243, 2024). "Lastly, Mst1 conditional knock-out (KO) mice were not used in the in vivo study; they should be used to confirm to confirm the effect of LIPUS on ICI-related myocarditis." (PMID 38236243, 2024).
nephrotic syndrome (1 paper, 2025). A collection of symptoms that include severe edema, proteinuria, and hypoalbuminemia; it is indicative of renal dysfunction. "Furthermore, we selected 3 NPH1 patients and 3 control patients with primary nephrotic syndrome and found that phosphorylated MST1/2, LATS1 and YAP levels in renal tissue were higher in NPH1 patients than in nephrotic syndrome patients." (PMID 39995111, 2025).
neurogenic muscle atrophy (1 paper, 2013). "Thus functioning upstream of FOXO3a transcription factor, MST1 kinase provides a potential therapeutic target for the clinical treatment of skeletal muscle atrophy." (PMID 23374633, 2013).
oral squamous cell carcinoma (1 paper, 2024). "In conclusion, our study revealed that lactate derived from cancer-associated fibroblasts promotes the CSCs phenotype in oral squamous cell carcinoma through the DLG5/CUL3/MST1 signaling axis." (PMID 39605072, 2024).
osteoporosis (1 paper, 2024). A condition of reduced bone mass, with decreased cortical thickness and a decrease in the number and size of the trabeculae of cancellous bone (but normal chemical composition), resulting in increased fracture incidence. "Collectively, identifying MST1/2 as key regulators of these genes offers insights to manage anti-tumor immunity or mitigate osteoporosis and SLE." (PMID 38624208, 2024). "MST1 and MST2 strongly suppress the expression of CTSK that is highly produced in osteoclasts, the bone macrophages, and have been a therapeutic target for treating osteoporosis." (PMID 38624208, 2024).
ovarian tumors (1 paper, 2024). "The ROC curve results demonstrate that the Hippo gene set, YAP1, and MST1 genes could predict the serous subtype ovarian tumors with better specificity and sensitivity with significant areas under the curve (AUC) and p values (p < 0.05)." (PMID 38730733, 2024).
pancreatic adenocarcinoma (1 paper, 2024). "Furthermore, it was shown that lncRNA MUF interacts with MST1, leading to the MST1 dephosphorylation by protein phosphatase 2A (PP2A) and increasing YAP1 nuclear localization in pancreatic adenocarcinoma." (PMID 38226210, 2024).
Papillary Thyroid Carcinoma (1 paper, 2011). "This in vivo study suggests that the direct interaction between BRAFV600E and MST1 could affect the behavior of papillary thyroid cancer." (PMID 21249150, 2011).
Parkinson disease (1 paper, 2024). A progressive degenerative disorder of the central nervous system characterized by loss of dopamine producing neurons in the substantia nigra and the presence of Lewy bodies in the substantia nigra and locus coeruleus. "We are currently conducting an in-depth investigation into the potential pathogenic link between Mst1/2 and Parkinson’s disease, including examination of the expression and genetic alterations of Mst1/2 in Parkinson’s disease patients and relevant models." (PMID 38443598, 2024). "Consistent with this notion, AAV-mediated Mst1 expression in the mouse SN ameliorated the pathological phenotypes of MPTP-induced Parkinson’s disease model mice." (PMID 38443598, 2024). "In addition, AAV-mediated Mst1 expression reduced the loss of TH-positive neurons, ameliorated behavioral deficits, and improved mitochondrial function in an MPTP-induced Parkinson’s disease mouse model." (PMID 38443598, 2024). "Interestingly, our findings in both Drosophila and the MPTP mouse model also suggest that Mst1/2 could be potential targets for Parkinson’s disease treatment." (PMID 38443598, 2024). "However, the therapeutic relevance of Mst1/2 in Parkinson’s disease requires careful validation." (PMID 38443598, 2024).
preeclampsia (1 paper, 2024). Preeclampsia is a hypertensive disorder of pregnancy that is characterized by new-onset hypertension with proteinuria presenting after 20 weeks of gestation, and depending on mild or severe forms may initially present with severe headache, visual disturbances, and hyperreflexia. "The rare variant rs71324987 in MST1 identified in these families might also be associated with preeclampsia based on functional annotation and in silico prediction." (PMID 38540995, 2024).
pulmonary congestion (1 paper, 2019). "We found that lung weight and indexed lung weight was elevated in Mst-1 mice consistent with pulmonary congestion, and AMD3100 reduced the indexed lung weight, consistent a reduction in pulmonary congestion." (PMID 30837882, 2019).
rectal cancer (1 paper, 2008). A primary or metastatic malignant neoplasm that affects the rectum.
Renal cyst (1 paper, 2025). A fluid filled sac in the kidney. "Moreover, the Kibra, p‐MST1/2, p‐LATS1 and p‐YAP were more positive in or around the renal cysts." (PMID 39995111, 2025).
respiratory distress syndrome (1 paper, 2014). "Mice specifically lacking MST1/2 in the respiratory epithelium exhibited phenotypes that are very reminiscent of peripheral lung immaturity and respiratory distress syndrome (RDS) which is the leading cause of mortality in preterm babies." (PMID 25097725, 2014).
retinal detachment (1 paper, 2020). An eye emergency condition which may lead to blindness if left untreated. "In MST1 and MST2 KO mice, MST2—but not MST1—was shown to be a critical regulator of caspase-mediated photoreceptor cell death in a mouse model of retinal detachment (RD)." (PMID 32140159, 2020).
rhabdoid tumor (1 paper, 2022). An aggressive malignant embryonal neoplasm usually occurring during childhood. "The two samples in this case, of the kidney and abdomen, were determined to share a single tumorigenic origin on the basis of shared SNVs in MST1 and LINGO4, in addition to the chr22 LOH event often observed in rhabdoid tumors." (PMID 35912263, 2022).
schwannoma (1 paper, 2020). A benign, usually encapsulated slow growing tumor composed of Schwann cells. "Only 2% and 1% of human schwannomas carry Lats1 and Lats2 mutations, respectively, and no Mst1/2 mutation has been reported in human cancer." (PMID 32960816, 2020).
scrapie (1 paper, 2014). A fatal disease of the nervous system in sheep and goats, characterized by pruritus, debility, and locomotor incoordination. "There was a trend to higher levels of activated JNK (p54; P-T183/Y185) and MST1 (P-T183) in the cortical region of scrapie-infected mice at 70 dpi (two-tail paired ratio t-test; JNK [p54], P = 0.0851; MST1, P = 0.0880)." (PMID 25183307, 2014). "At terminal stages of disease, levels of activated MST1 (P-T183) were higher in scrapie- than in mock-infected mice." (PMID 25183307, 2014). "Pro-survival CaMK4β/CREB signaling is activated in mouse scrapie at earlier times and later inhibited, whereas pro-death MST1 signaling is activated at these later times." (PMID 25183307, 2014). "Levels of activated MST1 (P-T183) were significantly higher (P = 0.0215) in the cortical region of scrapie-infected mice at terminal stages, when the levels of cleaved MST1 had returned to levels similar to those in mock-infected mice." (PMID 25183307, 2014). "The dysregulation of CaMK4β/CREB and MST1 signaling pathways may therefore be critical to the neurodegeneration in scrapie infected mice." (PMID 25183307, 2014). "MST1, DLK and mitogen-activated protein kinase 9 (JNK2) (p54; α2/β2 isoforms), which clustered together because they were expressed to similarly lower levels in scrapie- than in mock-infected mice at 130 dpi, are all involved in an MST1 signaling pathway that promotes neuronal death." (PMID 25183307, 2014). "In summary, MST1 signaling was activated in scrapie-infected mice at late times." (PMID 25183307, 2014). "Consistent with the lower expression levels of DLK (two-tailed paired ratio t-test; P = 0.0182), JNK2 (P = 0.0063), and MST1 (P = 0.0095), FOXO3 levels were also significantly lower (P < 0.0001) in the brainstem-cerebellum of scrapie- than of mock-infected mice at 130 dpi." (PMID 25183307, 2014). "However, MST1 and FOXO3 were still expressed to significantly lower levels in the cortical region of scrapie- than of mock-infected mice at 130 dpi (MST1, P = 0.0384; FOXO3, P = 0.0090)." (PMID 25183307, 2014). "The differential expression of MST1 and FOXO3 in the brainstem-cerebellum and cortical region, albeit to differing degrees, supports a model in which MST1/FOXO3 signaling is dysregulated during progression of scrapie." (PMID 25183307, 2014). "Levels of cleaved MST1 were significantly higher at 130 dpi in all brain regions (brainstem-cerebellum, P = 0.0452; subcortical region, P = 0.0237; cortical region, P = 0.0243), whereas activated JNK levels were similar in scrapie- and mock-infected mice at this time." (PMID 25183307, 2014).
skin cancer (1 paper, 2025). "Arsenic modulates Hippo pathway activity by upregulating key proteins like Large Tumor Suppressor Kinase 1/2 (LATS1), Salvador homologue-1 (Sav1) and ste20-like kinase 1/2 (Mst1), which are known to play roles in various cancers, including skin cancer." (PMID 40680435, 2025).
stomach adenocarcinoma (1 paper, 2015). "Examples include MST1/2 phosphorylation sites, MOB-binding domain, and the region critical for NF2 interaction; 3) In certain cancer types like stomach adenocarcinoma and uterine corpus endometrial carcinoma, mutation rates can be reasonably high (5.2%–5.9%)." (PMID 25482410, 2015).
systemic lupus erythematosus (1 paper, 2024). An autoimmune multi-organ disease typically associated with vasculopathy and autoantibody production. "Transcriptomic analyses identified differentially expressed genes (DEGs) regulated by MST1/2 that are enriched in biological pathways, such as systemic lupus erythematosus, tuberculosis, and apoptosis." (PMID 38624208, 2024).
systolic heart failure (1 paper, 2024). Heart failure caused by abnormal myocardial contraction during systole leading to defective cardiac emptying. "For example, forced expression of a constitutively active form of Yap in the adult heart stimulated cardiac regeneration and improves contractility after MI, while Hippo kinase pathway (Mst1, Lats2 and Mob1b) deficiency reversed systolic heart failure after MI." (PMID 38396885, 2024).
T-cell deficiency (1 paper, 2012). "MST1 deficiency has recently been described in seven patients from three unrelated kindreds with profound T-cell deficiency and various viral and bacterial infections." (PMID 22952854, 2012).
teratoma (1 paper, 2013). A non-seminomatous germ cell tumor characterized by the presence of various tissues which correspond to the different germinal layers (endoderm, mesoderm, and ectoderm). "Taken together our results showed that Mst1/Mst2 are required for proper cardiac lineage cell development and teratoma formation." (PMID 24224013, 2013). "It indicates that we can prevent teratoma formation from ES cells through inhibition of Mst1/Mst2 kinase activities, though further investigations are required to elucidate the mechanism of this." (PMID 24224013, 2013). "Taken together, our data suggest that Mst1/Mst2 are required for teratoma formation." (PMID 24224013, 2013). "RT-PCR examination of ES cells and teratoma revealed that the expression of Yap, Mst1 and Mst2 were higher in teratoma than ES cells, suggesting that Hippo pathway may play an important role in teratoma formation." (PMID 24224013, 2013). "Although it was reported that greater number of apoptotic cells were detected in Mst1/Mst2 double knockout embryos than Mst1/Mst2 single copy gene knockout embryos during E8.5 to E9.5, it was not for sure whether apoptosis were enhanced after ES cells were injected for teratoma." (PMID 24224013, 2013).
thymoma (1 paper, 2025). A neoplasm arising from the epithelial cells of the thymus. "MST1 cytoplasmic expression was higher in TCs compared to thymomas (Mann–Whitney U test, p = 0.014) and in the advanced tumor stage (Mann–Whitney U test, p = 0.002)." (PMID 40649713, 2025). "Moreover, when we compared the expression levels between B3 thymomas and TCs with the remaining histological types, B3 thymomas and TCs displayed a significantly higher MST1 expression (Mann–Whitney U test, p = 0.032)." (PMID 40649713, 2025). "Accordingly, cytoplasmic MST1 expression as well as nuclear and cytoplasmic LATS1 expression were significantly higher in TCs and B3 thymomas." (PMID 40649713, 2025).
thyroid (1 paper, 2010). "In our study we aimed to reveal the role of the classical RASSF members which harbor a C-terminal RA domain and a SARAH domain and their effectors MST1, MST2 and WW45 in thyroid carcinogenesis." (PMID 20920251, 2010).
turban tumor syndrome (1 paper, 2011). "The cylindromatosis/turban tumor syndrome gene (CYLD) on chromosome 16 ranked highest, followed by acylaminoacyl-peptidase (APEH), dystroglycan (DAG1), macrophage-stimulating protein (MST1) and ubiquitin-specific peptidase 4 (USP4), all located on chromosome 3." (PMID 21931648, 2011).
ventricular dilatation (1 paper, 2019). "In the current study, Mst1 mice had evidence of ventricular dilatation and reduced systolic function which was not altered by AMD3100." (PMID 30837882, 2019).
WHIM syndrome (1 paper, 2023). "HPV‐related papilloma cancer is seen in WHIM syndrome or EVER1, EVER2, MST1, RHOH, MAGT1, ITK deficiencies." (PMID 37102642, 2023).
tumor (197 papers, 2008 to 2026). "The role of MST1/2 as a tumor suppressor is well‐established, with loss of function leading to cell hyperproliferation and tumorigenesis." (PMID 40019375, 2025). "Our findings further confirm that Mst1/2-deficient NK cells exhibit impaired capacity against sensitive tumor cells and MHC-I-deficient target cells in vivo." (PMID 38898027, 2024). "While Mst1/2 double knockout (Mst1/2–/–) leads to embryonic lethality, conditional Mst1/2–/– in the liver or intestines causes enlarged tissues and tumor formation in mouse models (8, –, 11)." (PMID 38624208, 2024). "As a tumor suppressor gene, MST1 makes cells extremely susceptible to death receptor-mediated apoptosis through accelerating caspase-3 activation, which in turn promotes apoptosis." (PMID 38589525, 2024). "Upstream MST1 exerted its tumor-suppressive role in GC through a mechanism by which MST1 hindered the AMPK-Sirt3 pathway to cause excessive mitochondrial fission for cell death." (PMID 36289774, 2022). "Loss of MST1 activity results in tumor nodules formation in mouse livers, however the inactivation of MST1 in human HCC remains to be fully elucidated, although few regulators of MST1 have been proposed." (PMID 27765911, 2016). "Firstly, the mammalian Hippo pathway has redundant upstream negative regulators of YAP/TAZ (i.e. Mst1/2 and Lats 1/2) such that multiple mutations would be required to inactivate the pathway in a tumor." (PMID 25097728, 2014). "In some tumor cells, MST1/2 and LATS1/2 may prevent phosphorylation of YAP1, causing its translocation to the nucleus, where it functions as a transcription factor that promotes proliferation, invasion, and metastasis." (PMID 39313797, 2024). "Similarly, substantial defects were observed in the ability of Mst1/2-deficient NK cells to eliminate target RMA-S tumor cells." (PMID 38898027, 2024). "Furthermore, using a B16F10 lung metastasis tumor model, we discovered that compared to WT control mice, Mst1/2-deficient mice displayed significantly increased lung weight and tumor colony numbers." (PMID 38898027, 2024). "However, the presence of tumor appeared to prevent activation of Hippo signaling by maintaining PP2Ac association with and thereby inactivation of MST1/2." (PMID 36757811, 2023). "Loss-of-function of the tumor suppressors (MST1/2, LATS1/2, SAV1 etc.)and activation of transcriptional coactivators YAP/TAZ (caused by protein overexpression and/or enhanced nuclear accumulation) play important roles in tumorigenesis and cancer-associated malignant features." (PMID 33467099, 2021). "Moreover, we tested anti-PD1 therapy with regorafenib at 10 mg/kg against spontaneous HCCs developed in Mst1/Mst2-deficient mice and found that it significantly delayed tumor growth." (PMID 33234602, 2020). "Therefore, our results uncover a clinically relevant, targetable mechanism of FGFR4 oncogenic activity via suppression of the stress-associated MST1/2-induced apoptosis machinery in tumor cells with prominent HER/ERBB and FGFR4 signaling-driven proliferation." (PMID 30903103, 2019). "For example, MOB1-deficient animals develop the broadest range of tumours amongst all mice carrying manipulations of Hippo signalling components, suggesting that factors other than MST1/2, SAV, or LATS1/2 might play additional key roles." (PMID 25097725, 2014). "Furthermore, recent work demonstrated a role of MST1/2 kinases as tumor suppressors because combined deficiency of MST1/2 kinases leads to loss of the inactivation of YAP phosphorylation, massive liver overgrowth, and development of HCC." (PMID 23986776, 2013). "Such a feedback stimulation system, resulting in higher oxidant levels and DNA damage, might represent a tumor suppressor function of Mst1/2 to prevent the accumulation of mutations." (PMID 23985272, 2013).